THBS2 (thrombospondin 2)
Diseases named in the same sentence as THBS2 in open-access papers (continued):
Sharing a sentence is not in itself a finding about the gene and the disease.
hepatocellular carcinoma (8 papers, 2021 to 2025). A malignant tumor that arises from hepatocytes. "Chemotherapy enrichment for CD133 expressing cells with deficient THBS2 expression, which facilitates the promotion of cancer stemness properties in hepatocellular carcinoma (HCC) cells through extracellular matrix remodeling, is described." (PMID 33717837, 2021). "We evaluated the value of secreted glycoprotein thrombospondin-2 (TSP-2) to predict hepatocellular carcinoma (HCC) occurrence in chronic hepatitis C (CHC) patients after Hepatitis C virus (HCV) elimination by direct-acting antiviral agents (DAAs)." (PMID 36672412, 2023). "Secreted glycoprotein thrombospondin-2 (TSP-2) is a predictive biomarker of hepatocellular carcinoma (HCC) occurrence in chronic hepatitis C (CHC) patients after HCV elimination by direct-acting antiviral agents (DAAs)." (PMID 36672412, 2023). "In hepatocellular carcinoma, cancer stem cells lacking THBS2 promote tumor invasiveness and drug resistance by regulating matrix metalloproteinase (MMP) activity and matrix stiffness." (PMID 41174721, 2025). "This multicentre study investigated the dynamics of thrombospondin 2 (TSP2) levels during direct‐acting antiviral (DAA) therapy in hepatitis C virus (HCV) infected patients and evaluated TSP2's potential as a predictive marker for hepatocellular carcinoma (HCC)." (PMID 39403792, 2025).
liver disease (7 papers, 2019 to 2025). "Data from the GWAS study suggested that individuals with a pathogenic JAG1 variant and increased THBS2 expression could be at risk for developing more severe liver disease." (PMID 31343788, 2019). "Further investigation into the role of THBS2 in liver disease is therefore warranted." (PMID 35866482, 2022). "Unfortunately, we are unable to refer to other results concerning the activity of Thrombospondin 2 in the musculoskeletal system, as most studies on its role are currently being conducted on animals, while its usefulness as a marker has been confirmed in patients with liver disease." (PMID 41450968, 2025). "A second candidate genetic modifier, THROMBOSPONDIN2 (THBS2), was identified from a Genome Wide Association Study (GWAS) that stratified ALGS patients with pathogenic variants in JAG1 by whether they had mild or severe liver disease." (PMID 31343788, 2019).
non-small cell lung carcinoma (7 papers, 2016 to 2024). A group of at least three distinct histological types of lung cancer, including non-small cell squamous cell carcinoma, adenocarcinoma, and large cell carcinoma. "THBS2 is an extracellular matrix protein that has been implicated in various cardiovascular disorders and is also a candidate biomarker for non-small cell lung cancer." (PMID 38238732, 2024). "Of note, circulating levels of IGFBP7 and THBS2 have been associated with outcome in high-grade soft tissue sarcoma and non-small cell lung cancer, respectively." (PMID 27391064, 2016).
fibrosis (6 papers, 2019 to 2023). the formation of excess fibrous connective tissue in an organ or tissue in a reparative or reactive process. "Alternatively, THBS2 was chosen for its novelty in kidney fibrosis, while BSP and DSPP were selected to validate novel MCPs in fibrosis." (PMID 31723159, 2019).
pulmonary fibrosis (6 papers, 2021 to 2024). Chronic progressive interstitial lung disorder characterized by the replacement of the lung tissue by connective tissue, leading to progressive dyspnea, respiratory failure, or right heart failure. "A recent study identified that miR-17-5p contained exosomal derived from hESCs, which prevents pulmonary fibrosis through interaction with thrombospondin-2." (PMID 38739758, 2024). "More importantly, we identified that hESC-exo-derived miR-17-5p directly targeted Thbs2 to suppress pulmonary fibrosis by hindering collagen deposition." (PMID 37667335, 2023). "Repression of Thbs2 was accompanied by downregulation of fibrosis-associated proteins, including α-SMA, Fn, and collagen I. Our study is the first to identify that Thbs2 may be a potential target in the treatment of pulmonary fibrosis." (PMID 37667335, 2023). "Importantly, the present study suggests that miR-17-5p-loaded hESC-exo prevent pulmonary fibrosis by directly binding to Thbs2, which may offer a new therapeutic strategy for IPF, a disease currently lacking effective treatment." (PMID 37667335, 2023). "The mRNA expression of Itga11, Itgb8, Thbs1, and Thbs2 was significantly upregulated in the o-PF group, indicating the stronger activity of TGF-β in old rats when pulmonary fibrosis occurs." (PMID 36556326, 2022). "SPP1, THBS2, ITGB8, and some other genes screened out in this study have rarely been studied in the pathogenesis of pulmonary fibrosis, which also suggests possible approaches for subsequent pathogenesis studies." (PMID 33672678, 2021). "Taken together, the elevated levels of POSTN, THBS2, COL6A1, and LOXL1 may contribute to the development of pulmonary fibrosis, similar to what is seen in IPF, thus connecting fibrosis to inflammation in DM-ILD." (PMID 37928522, 2023). "The chronization of asthma and development of lung fibrosis was shown to either not affect observed asthma-driven upregulation of the genes, as in the case of Col1a1, Col4a1, and Col4a2, or downregulate the expression of Thbs2 and Tyrobp almost to the level of healthy control." (PMID 35625754, 2022).
COVID-19 (5 papers, 2021 to 2024). A disease caused by infection with severe acute respiratory syndrome coronavirus 2. "Furthermore, genetic susceptibility for IPF and COVID-19 seem to be similar, as confirmed by the fibrotic plasma biomarkers such as thrombospondin 2 (TSP2), glial-derived factor 15 (GDF15), insulin-like growth factor binding protein 7 (IGFBP7), and procollagen type III (PROC3)." (PMID 36966238, 2023). "The most convincing evidence for association with severe COVID-19 was found for five loci: two folate metabolic genes (MTHFR and MTR), two hemostasis inhibitor genes (PROC and ADAMTS13), and a thrombospondin gene (THBS2)." (PMID 34834519, 2021). "It is conceivable that the increased activity of SERPINF1 and THBS2 together with the high activity of HIF1A contribute to favoring of intussusceptive angiogenesis over conventional sprouting angiogenesis in the hypoxic environment of COVID-19 pulmonary involvement." (PMID 35163504, 2022). "Upregulation of astrocyte gene expression in glial fibrillary acidic protein (GFAP), thrombospondin 2 (Thbs2), leukemia inhibitory factor (Lif), and interleukin 6 (IL-6) by physical activity deserve further studies to explore whether it helps in immune responses, such as those against COVID-19." (PMID 39409085, 2024).
Nephropathy (5 papers, 2013 to 2023). A nonspecific term referring to disease or damage of the kidneys. "Thrombospondin-2 has been shown to act as a regulator of inflammation and matrix remodeling in experimental kidney disease and thrombospondin-2 gene therapy worsened the nephropathy." (PMID 33800255, 2021). "THBS2, NGAL and PIP levels might be good biomarkers for the association of T2DM with nephropathy." (PMID 27446820, 2015). "Using the tool of proteomic differential displays, we have identified that many plasma metabolic and inflammatory proteins such as THBS2, NGAL and PIP levels might be good biomarkers for the correlation to T2DM with nephropathy." (PMID 27446820, 2015). "We recently identified Thrombospondin-2 (TSP-2) as a regulator of matrix remodelling and inflammation in experimental kidney disease by using TSP-2 null mice and successfully proved TSP-2 overexpression as a therapeutic concept in a short term glomerulonephritis model in the rat." (PMID 24376766, 2013). "However, we did find that thrombospondin-2 (THBS2) levels were significantly higher in T2DM patients with nephropathy but not retinopathy." (PMID 27446820, 2015). "The lack of the matricellular protein thrombospondin-2 (TSP-2) in mice is known to accelerate renal injury: TSP2 is a major endogenous antiangiogenic and matrix metalloproteinase 2-regulating factor in renal diseases." (PMID 34359843, 2021). "Further, PIP, THBS2 and NGAL were significantly higher in T2DM patients with nephropathy (albuminuria) but not in those with retinopathy, while L1CAM levels were higher in T2DM patients with retinopathy." (PMID 27446820, 2015).
oral cavity squamous cell carcinoma (5 papers, 2017 to 2025). A squamous cell carcinoma arising from the oral cavity. "Some other studies also noted that THBS2 could act as a useful salivary marker for the detection of oral cavity squamous cell carcinoma." (PMID 36405394, 2022).
cholangiocarcinoma (4 papers, 2023 to 2025). A carcinoma that arises from the intrahepatic biliary tree (intrahepatic cholangiocarcinoma) or from the junction, or adjacent to the junction, of the right and left hepatic ducts (hilar cholangiocarcinoma). "Of note, both THBS2 and THBS5 had particularly high expression in lymphoid neoplasm diffuse large B-cell lymphoma (DLBC), thymoma (THYM) and gastrointestinal tumors, including cholangiocarcinoma (CHOL), CRC, PAAD, and STAD." (PMID 39732719, 2024).
colon adenocarcinoma (4 papers, 2020 to 2024). "THBS2, THBS3, THBS4, and THBS5 were differentially expressed in TGCT (testicular germ cell tumors) and COAD (colon adenocarcinoma)." (PMID 34804159, 2021). "For example, in colon adenocarcinoma (CAC), COL1A2, THBS2, and COL1A1 were related to prognosis." (PMID 33178362, 2020). "THBS1, THBS2 and THBS5 proteins exhibited relatively high expression in six cancer types compared to normal samples, except for THBS5 in clear cell renal cell carcinoma (CCRCC), while THBS3 and THBS4 proteins showed lower levels in colon adenocarcinoma (COAD) and HNSC." (PMID 39732719, 2024).
gastric tumor (4 papers, 2016 to 2025). "Similarly, previous transcriptomic analyses have documented increased THBS2 and E2F3 expression in advanced gastric tumors, which aligns with the significant overexpression detected across our datasets and validated in STAD cell lines." (PMID 41291892, 2025). "Moreover, several immunotherapies based clinical analyses have reported that stromal rich gastric tumors exhibit reduced responses to immune checkpoint inhibitors, which supports our observation that COL4A1 and THBS2 correlate with markers of an immune suppressive microenvironment." (PMID 41291892, 2025).
liver cancer (4 papers, 2016 to 2023). An epithelial or non-epithelial malignant neoplasm that arises from the liver. "The present study reveals the role of chemotherapy‐enriched CD133+ liver cancer stem cells (CSCs) with THBS2 deficiency." (PMID 33717837, 2021). "Analysis of data obtained in‐house and from a publicly available dataset (The Cancer Genome Atlas (TCGA), Liver Cancer (LIHC)) also showed THBS2 downregulation in HCC to be correlated with the worst recurrence‐free survival." (PMID 33717837, 2021).
metabolic syndrome (4 papers, 2022 to 2025). A cluster of metabolic risk factors for CARDIOVASCULAR DISEASES and TYPE 2 DIABETES MELLITUS. "THBS2 was also reported as a core gene in metabolic syndrome, a condition related to abnormal glucose and lipid metabolism." (PMID 38116696, 2023).
myxoid liposarcoma (4 papers, 2017 to 2025). A liposarcoma characterized by the presence of round non-lipogenic primitive mesenchymal cells and small signet ring lipoblasts within a myxoid stoma with a branching vascular pattern. "MiR-135b can target and inhibit the expression of thrombospondin 2 (THBS2) to increase the invasion and migration processes in myxoid liposarcoma in vitro and in vivo." (PMID 39736850, 2025).
nonalcoholic fatty liver disease (4 papers, 2022 to 2025). "The upregulation of THBS2 is positively related to inflammation in nonalcoholic fatty liver disease and fibrosis." (PMID 37366063, 2023).
Obesity (4 papers, 2020 to 2025). Accumulation of substantial excess body fat. "Other members of the EC matrix—thrombospondins—such as those identified in our study (THBS2, THBS3, and THBS4), are mainly detected in visceral adipose tissues and their increased expression level is associated with obesity." (PMID 32485856, 2020).
Sepsis (4 papers, 2019 to 2023). Sepsis is defined as life-threatening organ dysfunction caused by a dysregulated host response to infection. "MiR-106a promotes the sepsis-associated AKI via downregulating THBS2 in vivo." (PMID 34250012, 2021). "For example, miR‐191‐5p attenuates sepsis‐induced kidney injury via binding to oxidative stress‐responsive 1 (Qin, Wang, & Peng, 2019), and miR‐106a enhances sepsis‐mediated acute kidney failure by targeting THBS2 (Shen, Yu, Jing, & Zhang, 2019)." (PMID 32369227, 2020). "In order to study how miR-106a and THBS2 together affect sepsis-induced AKI in vitro, we used a complement experiment and simultaneously transfected siTHBS2 and miR-106a inhibitor into the LPS-treated TCMK-1 cells." (PMID 31432993, 2019). "In conclusion, miR-106a aggravates sepsis-induced AKI by targeting THBS2 in mice model and cells." (PMID 31432993, 2019). "It was reported that serum miR-106a was increased in sepsis-induced AKI mice, and miR-106a was suggested to target thrombospondin 2 (THBS2), leading to inflammation and apoptosis." (PMID 37761260, 2023). "MiR-106a might be an ideal test and evaluation index, and further research on the downstream targeting gene THBS2 might provide a broader approach and method for the diagnosis and treatment of AKI caused by sepsis, the development of molecular targeted drugs and prognosis of sepsis patients." (PMID 31432993, 2019). "In recent years, studies have shown that THBS2 plays an important role in tumors, but no studies related to sepsis have been reported." (PMID 31432993, 2019).
type 2 diabetes (4 papers, 2021 to 2023). "Serum circulating levels of thrombospondin-2 have been associated with increased incidence of hypertensive heart failure and worsening diastolic function in patients with type 2 diabetes." (PMID 37484982, 2023). "Circulating thrombospondin-2 has already been explored as a potential marker of fibrosis in nonalcoholic fatty liver disease in type 2 diabetes." (PMID 37484982, 2023).
viral myocarditis (4 papers, 2016 to 2022). Myocarditis that is caused by an infection with a viral agent. "THBS2 and THBS4 isoforms have been shown to protect ECM adverse remodeling in ageing heart and viral myocarditis induced HF." (PMID 27635260, 2016).
breast tumors (3 papers, 2022 to 2025). "In fact, in tumor extracellular matrix proteomic analysis from breast tumors, THBS2, followed by FBLN1 and COL1A1, have the highest correlation with collagen fiber alignment, an ECM trait predictive of shorter disease-free survival." (PMID 35159353, 2022). "We compared the differentially expressed genes between the four types of organ metastases and primary breast tumors and identified genes such as COL11A1, MMP11, and THBS2 as more frequently differentially expressed in metastatic sites." (PMID 40500539, 2025). "In the context of tumor evasion, aberrant upstream THBS1 and THBS2 provoke overactivation of MGAT1, leading to enhanced CD73 glycosylation and membrane-bound accumulation, especially in immune-cold breast tumors." (PMID 40229283, 2025).
cardiomyopathy (3 papers, 2012 to 2022). A disease of the heart muscle or myocardium proper. "When they overexpressed thrombospondin-2 (TSP-2) using AAV9-CMV-TSP vectors in the hearts of TSP-2 null mice they were able to rescue accelerated age-induced cardiomyopathy completely." (PMID 22586493, 2012).
cervical squamous cell carcinoma (3 papers, 2022 to 2024). A squamous cell carcinoma arising from the cervical epithelium. "Cervical squamous cell carcinoma-cell-derived exosomes delivered miR-221-3p from cancer cells to the human umbilical vein endothelial cells (HUVECs), and the exosomal miR-221-3p promoted angiogenesis via downregulation of Thrombospondin-2 in cervical squamous cell carcinoma." (PMID 35024437, 2022). "In cervical squamous cell carcinoma, cancer-derived exosomal miR-221-3p can directly bind to the 3′ UTR region of thrombospondin 2 (THBS2) mRNA to decrease its expression and thereby provoke angiogenic effect." (PMID 35592419, 2022). "Compared to normal tissues, THBS1 and THBS2 showed higher expression in brain cancers and PAAD, but lower expression in cervical squamous cell carcinoma and endocervical adenocarcinoma (CESC), OV, uterine corpus endometrial carcinoma (UCEC) and uterine carcinosarcoma (UCS)." (PMID 39732719, 2024).
Cirrhosis (3 papers, 2022 to 2025). A chronic disorder of the liver in which liver tissue becomes scarred and is partially replaced by regenerative nodules and fibrotic tissue resulting in loss of liver function. "THBS2 was elevated in individuals with cirrhosis compared with NAFL and the population, and ACY1 in individuals with NAFL compared with the general population." (PMID 36280732, 2022). "Using UKB (Olink), the most significant difference between NAFL and cirrhosis was, first, for thrombospondin 2 (THBS2, P = 6.6 × 10−114, effect = 1.59 s.d)." (PMID 36280732, 2022). "Although some studies have shown that proteins such as THBS2, IGFBP7, and IGFPB2 are differentially expressed between MASLD and cirrhosis." (PMID 40282358, 2025).
diabetic kidney disease (3 papers, 2023 to 2026). Progressive kidney disorder caused by vascular damage to the glomerular capillaries, in patients with diabetes mellitus. "DDIT3, GADD45A, THBS2, CCL2, and CSF1R showed consistent expression trends across platforms, and are known mediators of inflammation, extracellular matrix remodeling, and stress responses in diabetic kidney disease." (PMID 41481573, 2026).
endometrial cancer (3 papers, 2010 to 2024). Primary or metastatic malignant neoplasm involving the endometrium (mucous membrane that lines the endometrial cavity). "Other genes inactivated by promoter hypermethylation in endometrial cancer include PgR, the cell cycle control genes 14-3-3 sigma, homeobox gene HOXA11, thrombospondin-2 gene (THBS2), paternally expressed gene 3 (PEG3), as well as the detoxifying enzyme glutathione S-transferase P1 (GSTP1)." (PMID 20396392, 2010).
endometriosis (3 papers, 2020 to 2026). The growth of functional endometrial tissue in anatomic sites outside the uterine body. "Lower PNX-14 levels, typical in endometriosis patients, were associated with reduced THBS2 expression, potentially driving increased transformation activity and inversely correlating with cell viability." (PMID 39857742, 2025). "THBS2 expression decreased under both physiological and endometriosis-specific concentrations of PNX-14." (PMID 39857742, 2025). "Moreover, we observed a strong negative correlation between the viability of 12Z cells (XTT assay) and the expression of CDH1 and THBS2 in cells treated with PNX-14 at endometriosis-specific concentrations." (PMID 39857742, 2025). "Taken together, decreased THBS2 expression, accompanied by increased cell metabolism, might be one of the mechanisms through which endometriosis-specific concentration of PNX-14 in a GPR173-dependent manner modulates the viability and apoptosis of epithelial cells." (PMID 39857742, 2025).
fatty liver (3 papers, 2018 to 2024). "However, the other liver steatosis gene markers, such as Thbs2, Lum, Lamc3, Lama2, Akr1b10, Col4a4, A2m, and C7, were not significantly different between the db-HF and db-HC groups." (PMID 38613031, 2024). "It has been proved that the gene expression of THBS2 increased in fatty liver of NAFLD." (PMID 34419146, 2021). "To further determine which genes might play a significant role in the progression of fatty liver, we used real-time qPCR to detect the expression of 8 DEGs using clinical samples, including CD24, PZP, COL1A1, COL1A2, LUM, VCAN, THBS2 and EPHA3." (PMID 29769552, 2018).